STAT3 (signal transducer and activator of transcription 3)
Diseases named in the same sentence as STAT3 in open-access papers (continued):
Sharing a sentence is not in itself a finding about the gene and the disease.
lung carcinoma (continued). "In the study, we found IL-11 facilitated lung cancer cell chemoresistance via IL-11R/STAT3 signaling pathway which promoted anti-apoptosis protein activation." (PMID 27922075, 2016). "It has previously been shown that the mitochondrial uncoupling protein 2 regulates the ROS/Stat3 signaling pathway and responds to the chemotherapy in lung cancer cells." (PMID 27101310, 2016). "This is the first report that GA inhibits Src-mediated Stat3 signaling contributing to the TKI resistance in lung cancer." (PMID 27419630, 2016). "Mechanistically, we demonstrated that GA suppression of Src-mediated Stat3 signaling is important for the anti-tumorigenic effect in TKIR lung cancer." (PMID 27419630, 2016). "The IL-6/STAT3 pathway was also shown to increase tumor-initiating activities in murine colon and lung cancer cell lines by milk fat globulin epidermal growth factor-8 (MFGE-8)." (PMID 26980947, 2016). "This study investigates how lung cancer increases the activation and DNA binding activity of STAT3, which in turn enhances the expression of IL-10 in DCs." (PMID 27833081, 2016). "This study demonstrates that laricitrin provides the highest level of efficacy to improve lung cancer-mediated DC suppression through the down-regulation of the STAT3/IL-10 signaling pathway." (PMID 27833081, 2016). "We showed that miR-1207-5p inhibited lung cancer cell A549 proliferation, migration and invasion in vitro, and suppressed the STAT3 and AKT signalings." (PMID 27107415, 2016). "To investigate the potential role of STAT3 and TrkB activation in the biology of lung cancer, we analyzed the rates of A549 and H1299 cell proliferation upon treatment with Stattic or/and K252a by CCK8 assay." (PMID 27456333, 2016). "Reversal of laricitrin on lung cancer-induced DCs’ paralysis was via inhibiting the phosphorylation of signal transducer and activator of transcription 3 (STAT3)." (PMID 27833081, 2016). "In the context of lung cancer, STAT3 prevented disease initiation by maintaining pulmonary homeostasis under oncogenic stress." (PMID 27577070, 2016). "EMSA analysis also revealed that A549- and CL1-5-CM increased the DNA binding activity of STAT3, and laricitrin reduced the lung cancer-induced enhancement of STAT3 on DNA binding capacity in CD14+ monocytes." (PMID 27833081, 2016). "Laricitrin decreases the lung cancer-mediated activation of STAT3, subsequently reducing IL-10 levels in DCs." (PMID 27833081, 2016). "Specifically in lung cancer, STAT3 has been shown to function as one of the main downstream transcription factors in EGFR mutant ACs13 and to act as an oncogene in a chemically induced mouse model of lung cancer." (PMID 25734337, 2015). "We next investigated the ability of BSN can modulate constitutive STAT3 activation in a variety of human lung cancer cell lines." (PMID 25788267, 2015). "Though lung cancer is the most common source of BM, there is very little data supporting the role of STAT3 and miR-21 in BM progression." (PMID 26314961, 2015). "Recently, this autocrine mechanism was demonstrated in human lung cancer cells secreting IL-22- and IL-6- induced STAT3 phosphorylation, thus contributing to the pathogenesis of lung adenocarcinoma and formation of pleural effusion." (PMID 25793261, 2015). "Studies of the IL-6 mechanism of action suggests that IL-6 promotes lung cancer cell proliferation and migration through activation of the transcription factor Signal Transducer and activator of Transcription 3 (STAT3)." (PMID 26517240, 2015). "The results described here in human, complement also data from murine models of lung cancer, which have shown that IL-6/STAT3 signaling facilitates cancer progression by promoting cell growth." (PMID 26486080, 2015).
lung carcinoma (continued). "As a previous study indicated that JAK1 is the critical JAK kinase contributing to STAT3 activation and mediates IL-6-induced STAT3 activation in lung cancer cells, we next determined the effect of NOX4 overexpression on JAK1/STAT3 activity in A549 cells." (PMID 25504436, 2015). "A recent study demonstrates that inhibition of EGFR by erlotinib, an EGFR inhibitor results in activation of the STAT3 signaling in lung cancer cells." (PMID 25669984, 2015). "The release of inflammatory cytokines such as interferon-gamma (IFN-γ) activates the signal transducer and activator of transcription 3 (STAT3) pathway and subsequently upregulates PD-L1 expression on lymphoma and lung cancer cells." (PMID 25889536, 2015). "STAT3 is considered to play an oncogenic role in several malignancies including lung cancer; consequently, targeting STAT3 is currently proposed as therapeutic intervention." (PMID 25734337, 2015). "We found that brassinin (BSN) suppressed both constitutive and IL-6-inducible STAT3 activation in lung cancer cells." (PMID 25788267, 2015). "In the rat lung cancer model, the expression of NF-κB, STAT3, or cyclinD1 was knocked down before carcinogen exposure and the tumorigenic rate was decreased by varying degrees accordingly." (PMID 25823926, 2015). "EGFR and KRAS mutations, activation of Src kinase, and elevated expression of interleukin-6 (IL-6) are among several molecular aberrations have been identified in lung cancer that often result in the activation of STAT3." (PMID 26314961, 2015). "PIAS3 has been known to control STAT3 transcriptional activity in lung cancer cells through affecting its DNA transcriptional properties and STAT3 phosphorylation." (PMID 25788267, 2015). "It has been reported that miR-10a silencing reverses cisplatin resistance in human lung cancer cell lines via the transforming growth factor-β/Smad2/STAT3/STAT5 pathway." (PMID 26317552, 2015). "In conclusion, crizotinib can induce cytoprotective autophagy by suppression of STAT3 in lung cancer cells." (PMID 26384345, 2015). "Bcl-2 and Bcl-xl expression are mainly regulated by STAT3 pathway, and these proteins are overexpressed in lung cancer cells." (PMID 25788267, 2015). "We have demonstrated that STAT3 has a tumour-suppressor function in murine Kras mutant lung cancer as well as in human KRAS mutant xenografts." (PMID 25734337, 2015). "In this study, we found that crizotinib induced a high level of autophagy in lung cancer cells through inhibition of STAT3." (PMID 26384345, 2015). "Taken together, these findings suggest that crizotinib induces autophagy in targeted lung cancer cells in vivo through the inhibition of the phosphorylation of the STAT3 signaling pathway." (PMID 26384345, 2015). "In summary, we conclude that crizotinib can activate autophagy in lung cancer cells through a STAT3-dependent mechanism in a step-wise manner." (PMID 26384345, 2015). "Activation of STAT3 by IL6, or overexpression of total or phosphorylated STAT3 significantly suppressed crizotinib-induced autophagy in lung cancer cells." (PMID 26384345, 2015). "In the present study, we first demonstrated that crizotinib activated autophagy in lung cancer cells through the inhibition of cytoplasmic as well as nuclear STAT3 signaling." (PMID 26384345, 2015). "In conclusion, our data indicate that aberrant Akt signalling contributes to maintaining stemness in lung cancer TICs through a NF-kB/IL-6/STAT3 pathway and provide novel potential therapeutic targets for eliminating these malignant cells in NSCLC." (PMID 26486080, 2015). "Recently, Muller and colleagues have demonstrated how SIAH2 accelerates the proteasomal degradation of TYK2, leading to STAT3 inactivation in lung cancer cells." (PMID 26580787, 2015). "STAT3 is an intracellular transducer of cytokine signals that cooperates with Ras in tumour formation and is often activated in lung cancer." (PMID 25734337, 2015).
lung carcinoma (continued). "The results indicated that the phosphorylation of Src Y418, EGFR Y1068 and STAT3 Y705 was reduced in a dose-dependent manner (50–500 nM) by digoxin in the A549 lung cancer cell line that possesses wild-type EGFR." (PMID 25955608, 2015). "Recent studies have shown that STAT3 directly binds to the promoter region of Beclin1 in lung cancer." (PMID 25638155, 2015). "Constitutive activation of STAT3 in both lung cancer cell lines and lung cancer tissues has been implicated in the malignant progression of lung cancer and high expression of STAT3 and phosphorylated-STAT3 are strong predictors of poor patient prognosis." (PMID 26314961, 2015). "STAT3 activation is related to angiogenesis, cell survival, immunosuppression and tumor invasion in lung cancer." (PMID 25198511, 2014). "Lung cancers often carry constitutively active tyrosine phosphorylated STAT3 (abbreviated as pSTAT3) induced by JAK1 or JAK2 and the JAK2-STAT3 signaling node is a major oncogenic driver in lung tumors." (PMID 24833526, 2014). "There have been clinical trials testing STAT3 inhibitors, including upstream TKIs for solid tumors, such as lung cancers." (PMID 24675568, 2014). "Inhibition of the STAT3 pathway has been shown to overcome resistance of lung cancer, head and neck cancer, pancreatic cancer, and glioma to anti-EGFR therapy." (PMID 24662938, 2014). "Our results have consolidated the role of KIF5B-RET fusion gene in the pathogenesis of NSCLC and identified STAT3 as a key mediator of the transforming activity of KIF5B-RET positive lung cancer cells." (PMID 25047660, 2014). "Whereas it was found STAT3 acted as a JAK1/JAK2-induced oncogenic driver in lung cancers, STAT1 expression was reported to form part of a genetic signature predicting event-free and overall survival of lung cancer patients." (PMID 24833526, 2014). "CuB also induced lung cancer cell apoptosis through cytochrome c release, Bcl-2 downregulation and STAT3 pathway inhibition." (PMID 25242136, 2014). "Curcumin as a non-specific STAT3 inhibitor reduces cell proliferation and colony formation in cell culture and preclinical model in lung cancer via reducing the phosphorylation of STAT3 and inhibit the activation of STAT3." (PMID 24743778, 2014). "The ambivalent role of STAT1 and STAT3 in lung cancer prompted us to analyze if the TYK2-dependent activation of the reporter is mediated by STAT1 or STAT3." (PMID 24833526, 2014). "Most importantly, high IDO1, STAT3 and CYP1B1 expression was associated with reduced relapse-free survival in lung carcinoma patients." (PMID 24657910, 2014). "Treatment of HCC2429 and H460 lung cancer cells with the JAK2 inhibitor TG101209 led to a reduced phosphorylation of STAT3, inhibition of survivin, increased apoptosis, and decreased cell proliferation." (PMID 25268165, 2014). "The expression of STAT3 also correlates with another highly potent angiogenic factor called basic-Fibroblast Growth Factor (bFGF) both tumor-derived myeloid cell lines, lung cancer cell lines as well as lung cancer patient samples." (PMID 24722453, 2014). "The decoy which corresponds to the STAT3 response element in the c-fos promoter and binds competitively to STAT3 has been shown to inhibit the growth of human lung cancer." (PMID 24675568, 2014). "Inhibiting STAT3 activity with siRNA or a small-molecule inhibitor dramatically sensitized lung cancer cells to treatment with AZD6244 both in vitro and in vivo." (PMID 24662938, 2014). "The relevance of the IDO-AHR-IL-6-STAT3 transcriptional circuit is underscored by the finding that high expression of its members IDO, STAT3 and the AHR target gene CYP1B1 is associated with reduced relapse-free survival in lung cancer patients." (PMID 24657910, 2014).
lung carcinoma (continued). "These events induce recruitment of the scaffolding protein, Gab1, to the plasma membrane and consequent recruitment/activation of PI3 kinase, Akt and STAT3 signaling which are required for human lung cancer proliferation, migration and EMT." (PMID 24662916, 2014). "Aberrant expression and constitutive activation of STAT3 are involved in a broad range of human malignancies, including gastric, breast, prostate, and nonsmall cell lung cancers." (PMID 24864251, 2014). "It has been recently reported that inhibition of EGFR by erlotinib activates the STAT3/Bcl2/Bcl-XL survival signaling pathway in human lung cancer." (PMID 24019973, 2013). "Considering the pivotal role of STAT3 and Akt in anti-apoptotic machinery, our study answers, at least partly, why certain types of lung cancer cells are resistant to gefitinib-induced cell death." (PMID 24280348, 2013). "We have previously revealed increased levels of IL-6 and subsequent activation of the STAT3 pathway in our K-ras induced mouse model of lung cancer in absence and presence of COPD-like airway inflammation." (PMID 24321240, 2013). "Combinational STAT3 inhibition significantly fortifies the anti-cell growth effects of gefitinib in lung cancer cells compared to the group of gefitinib alone (P<0.01 in both tests)." (PMID 24280348, 2013). "In our study, the regulation of TF by IL-6/JAK2/Stat3 signaling, which participates in metastasis, was also confirmed in lung cancer cells." (PMID 24086497, 2013). "The protective effect of IL-22 is consistent with a previous report that IL-22 contributes to the chemotherapeutic resistance of human lung cancer cells through the activation of STAT3." (PMID 23519428, 2013). "By establishing a STAT3 signal based high-throughput drug screening system in human lung cancer A549 cells, we have screened a library from natural products which contained purified compounds from medicinal herbs." (PMID 23704931, 2013). "It is likely that lung cancer cells take advantage of or even strengthen this gefitinib-induced STAT3-Akt axis through long term exposure to gefitinib in order to gain resistance to it." (PMID 24280348, 2013). "For example, GemiNI analysis of a lung cancer data set with paired gene/miRNA expression (GSE18805,) identified top TFs (CREB1, SP1 and STAT3) and miRNAs (miR-15a, miR-195 and miR-497) that are dysregulated in lung cancer." (PMID 23418540, 2013). "In summary, this report shows that CHI3L1 is a potential biomarker for inflammation-induced lung cancer prediction in animal models, especially in Stat3-induced cancer." (PMID 23613996, 2013). "Here, we report that secretory protein Chitinase 3-Like 1 (CHI3L1), a Stat3 downstream gene product, is a potential biomarker for lung cancer prediction in various animal tumor models and humans." (PMID 23613996, 2013). "Taken together, our data clearly demonstrate that autocrine IL-6-induced Stat3 activation regulates membrane TF expression in lung cancer cells." (PMID 24086497, 2013). "Altogether, our data indicate that suppression of Stat3-induced TF expression in lung cancer cells decreased colony formation in vitro, as well as cell adhesion, lung metastasis in vivo." (PMID 24086497, 2013). "We have recently identified additional secretory proteins that are products of Stat3 downstream genes as biomarkers for lung cancer for this purpose." (PMID 23613996, 2013). "It is important to keep in mind that the CHI3L1 upstream Stat3 oncogene is up-regulated in both human lung cancer and COPD." (PMID 23613996, 2013). "Together, our data showed that inhibition of Stat3 activation or knockdown of TF expression in lung cancer cells decreased colony formation ability." (PMID 24086497, 2013). "PLGA nanoparticles were developed to codeliver paclitaxel and Stat3 siRNA to overcome cellular resistance in lung cancer cells." (PMID 23527297, 2013).
lung carcinoma (continued). "In our study, we showed that surface TF expression was regulated by IL-6/Stat3 signaling, and TF-induced coagulation was decreased by inhibiting Stat3 activation in lung cancer cells." (PMID 24086497, 2013). "Given the increasing evidence supporting clinical application of STAT3 inhibitors as therapeutic agents in treating various cancers, our findings underscore the relevance of targeting STAT3 in lung cancer therapy from at least two perspectives." (PMID 22723956, 2012). "On the contrary, Stat3 inhibition in lines displaying extensive GJIC (QU-DB, SK-LuCi6) suppressed junctional permeability, indicating that Stat3 activity is actually required for the maintenance of gap junction function in these lung cancer lines." (PMID 23244248, 2012). "The JAK/STAT signaling axis is a key modulator of cytokine signaling and one proposed mechanism for aberrant STAT3 activation in lung cancer involves the upregulation of autocrine and/or paracrine IL-6 signaling." (PMID 21533169, 2011). "IL-22 also protected lung cancer cell lines from serum-starvation-induced and chemotherapeutic drug-induced apoptosis by activation of STAT3 and its downstream antiapoptotic proteins and inhibition extracellular signal-regulated kinase 1/2." (PMID 21625390, 2011). "We recently showed that a principal mechanism of Stat3 activation in breast and lung cancers is through autocrine production of IL-6." (PMID 20929542, 2010). "IL-6 has been demonstrated as a potent activator of the JAK/STAT3 pathway, and has been shown to act in an autocrine manner to induce STAT3 to contribute to the pathogenesis of lung cancer." (PMID 18939993, 2008). "We next investigated the molecular mechanisms by which STAT3 decoy ODN inhibited growth of lung cancer cells." (PMID 17683579, 2007). "In present study, we used STAT3 decoy ODN to turn down the constitutively activated STAT3 in lung cancer cells." (PMID 17683579, 2007). "STAT3 decoy ODN was effectively transfected into A549 lung cancer cells and mainly located in nucleus." (PMID 17683579, 2007). "The in vivo efficacy of STAT3 decoy ODN was tested using nude mice bearing human A549 lung carcinoma xenografts." (PMID 17683579, 2007). "Both in vitro and in vivo experimental results demonstrated the potential values of STAT3 decoy ODN approach in the treatment of lung cancer." (PMID 17683579, 2007). "In summary, we have provided evidence that STAT3 decoy ODN suppresses growth of lung cancer cells in vitro and in vivo through affecting the balance between cell proliferation and rate of apoptosis." (PMID 17683579, 2007). "STAT3 was phosphorylated on Tyr705 and Ser727 in A549 lung cancer cells, which was consistent with our previous observation in human pulmonary giant cell carcinoma cell line PG." (PMID 17683579, 2007). "For in vivo experiment, A549 lung carcinoma-nude mice xenograft was used as a model to examine the effect of the STAT3 decoy by intratumoral injection." (PMID 17683579, 2007). "Restoration of suppressors of cytokine signalling-3 (SOCS-3), which is frequently silenced by hypermethylation in lung cancer cells, resulted in the down-regulation of activated STAT3, leading to induction of apoptosis and growth suppression." (PMID 17683579, 2007). "In the present study, we demonstrate that STAT3 decoy ODN can suppress lung cancer cells in vitro and in vivo by efficiently blocking STAT3 signaling, suggesting the therapeutic potential of STAT3 decoy ODN in treatment of human lung carcinoma." (PMID 17683579, 2007). "GMI can also regulate p-STAT3 (STAT3 activation state) in lung cancer cells." (PMID 41438583, 2026). "Aminoflavone 8 enhanced NK-92MI cell cytotoxicity, as evidenced by the elevated expression of cytotoxic effectors, such as IFN-γ, perforin, and granzyme B. Aminoflavone 8 also inhibited STAT3 phosphorylation in A549 lung cancer and NK-92MI cells under co-culture conditions." (PMID 41688864, 2026).